TMEM160 (transmembrane protein 160)
Synonyms: FLJ20512
Tractability: Antibody: UniProt predicts a signal peptide or a membrane-spanning region.
Gene: Protein-coding gene on chromosome 19 (47,045,909 to 47,048,624, reverse strand). Ensembl gene ENSG00000130748.
Subcellular location: Mitochondrion inner membrane
Gene Ontology:
Molecular function: protein binding
Cellular component: mitochondrial inner membrane; mitochondrion
Genetic constraint (gnomAD): Loss-of-function variants: 14 observed, 8.84 expected, observed/expected ratio (o/e) 1.58, 90% interval 1.01 to 1.94. That is too few expected variants to judge how well the gene tolerates losing a copy. Missense variants: 287 observed, 196.35 expected, observed/expected ratio (o/e) 1.46, 90% interval 1.33 to 1.61. Synonymous variants: 159 observed, 98.76 expected, observed/expected ratio (o/e) 1.61, 90% interval 1.41 to 1.83.
Homologues: Orthologues: chimpanzee TMEM160 (99% identical), mouse Tmem160 (94% identical), pig TMEM160 (94% identical), rat Tmem160 (94% identical), dog TMEM160 (93% identical), guinea pig TMEM160 (92% identical), macaque TMEM160 (57% identical), zebrafish tmem160 (41% identical).
Diseases named in the same sentence as TMEM160 in open-access papers:
TMEM160 is named in the same sentence as 15 diseases in open-access papers, as found by Europe PMC text mining. Sharing a sentence is not in itself a finding about the gene and the disease. The quoted sentences say what the papers report.
colorectal cancer (2 papers, 2024 to 2025). A primary or metastatic malignant neoplasm that affects the colon or rectum. "Recently, TMEM160 was linked to immune evasion in tumors and resistance to radiotherapy in colorectal cancer." (PMID 39940865, 2025). "It has been documented that TMEM160 promotes radiotherapy resistance in colorectal cancer cells through immune system evasion." (PMID 39940865, 2025).
Obesity (2 papers, 2013 to 2025). Accumulation of substantial excess body fat. "Variants at MTCH2, LRRN6C and TMEM160 were also nominally associated with overweight or obesity risk." (PMID 23347264, 2013). "TMEM160 is linked to human obesity and lipid metabolism in dairy cows." (PMID 41459085, 2025).
cervical cancer (1 paper, 2025). A primary or metastatic malignant neoplasm involving the cervix. "We investigated the subcellular localization of endogenous TMEM160 in various lung and cervical cancer cell lines (A549, H1975, HeLa, and SiHa) and corresponding non-tumor cell lines (BEAS and HaCaT)." (PMID 39940865, 2025). "In summary, we report here that the expression of TMEM160 is upregulated in lung cancer and cervical cancer cells." (PMID 39940865, 2025). "Our study demonstrates that TMEM160 is significantly upregulated in lung adenocarcinoma and cervical cancer, where it is found in both the cytoplasm and nucleus of cancer cells." (PMID 39940865, 2025). "Our findings demonstrated that TMEM160 knockdown decreased the proliferation of lung and cervical cancer cell lines." (PMID 39940865, 2025). "This study provides an initial understanding of the function of TMEM160 in lung and cervical cancer progression and clarifies the need to continue investigating the participation of TMEM160 in these cancers." (PMID 39940865, 2025). "This study aimed to investigate the role of TMEM160 in non-small cell lung cancer and cervical cancer using cell lines, clinical samples, and xenograft studies." (PMID 39940865, 2025). "In our study, we identified TMEM160 as a critical factor in lung adenocarcinoma (LUAD) and cervical cancer." (PMID 39940865, 2025). "In this study, we investigated the role of TMEM160 in lung adenocarcinoma (LUAD) and cervical cancer." (PMID 39940865, 2025). "Our study highlighted the biological functions of TMEM160 in LUAD and cervical cancer and suggested its potential value as a therapeutic target for LUAD and cervical cancer treatment." (PMID 39940865, 2025). "Although the exact mechanism remains unknown, our findings suggest that further investigation is needed to determine how TMEM160 influences tumor progression and promotes the growth of tumor cells in LUAD and cervical cancer." (PMID 39940865, 2025). "However, the specific expression and function of TMEM160 have not been studied in lung and cervical cancers." (PMID 39940865, 2025). "However, the role of TMEM160 in lung and cervical cancers has not been elucidated." (PMID 39940865, 2025).
cervical tumor (1 paper, 2025). "A key finding of our study is the first-time demonstration that endogenous TMEM160 is localized predominantly in the nucleus and, to a lesser extent, in the cytoplasm of lung and cervical tumor and non-tumor cell lines, displaying dynamic localization patterns during cell division." (PMID 39940865, 2025).
gastric tumor (1 paper, 2025). "In this study, we found that TMEM160 was markedly overexpressed in clinical gastric tumor tissues, and its elevated expression was significantly associated with poor prognosis." (PMID 40223081, 2025).
lung adenocarcinoma (1 paper, 2025). A carcinoma that arises from the lung and is characterized by the presence of malignant glandular epithelial cells. "We found that the intense staining indicates a high expression level of TMEM160 in lung adenocarcinoma tissues, as well as in adenocarcinoma and squamous cell carcinoma cervical tissues." (PMID 39940865, 2025). "To elucidate the role of TMEM160 in lung adenocarcinoma (LUAD), we performed co-immunoprecipitation (Co-IP) followed by mass spectrometry (LC-MS/MS) to identify proteins interacting with TMEM160 in the A549 cell line." (PMID 39940865, 2025).
lung carcinoma (1 paper, 2025). "To substantiate the potential role of TMEM160 in the pathogenesis and progression of lung cancer, we used the CRISPR/Cas9 system to silence the expression of TMEM160 in A549 cells (KO TMEM160)." (PMID 39940865, 2025).
cancer (4 papers, 2025 to 2026). A tumor composed of atypical neoplastic, often pleomorphic cells that invade other tissues. "We also found that the TMEM160 interactome is associated with xenobiotic metabolism, closely related to chemoresistance in cancer cells." (PMID 39940865, 2025). "Our findings emphasize the ROS-related pathways, indicating that TMEM160 may be linked to cellular stress responses, enabling cancer cells to survive in hostile environments." (PMID 39940865, 2025). "We observed that TMEM160 is localized in the nucleus and cytoplasm and dynamic localization during mitosis of cancer cells and discovered a novel interaction between TMEM160 and nuclear proteins such as NUP50." (PMID 39940865, 2025). "The significant interaction of nuclear proteins and TMEM160 aligns with their nuclear localization and suggests potential functions that favor cancer cells." (PMID 39940865, 2025). "Through TCGA database analysis, we identified TMEM160 as a pan-cancer upregulated gene, with significant mRNA elevation in GC and other solid tumors." (PMID 40223081, 2025). "Additionally, TMEM160 knockout leads to increased reactive oxygen species (ROS) production and induces a mitochondrial unfolded protein response, indicating that TMEM160 inhibits ROS production in cancer cells." (PMID 40223081, 2025).
tumor (4 papers, 2024 to 2025). "To confirm the effect of TMEM160 on tumor growth in vivo, we conducted animal experiments in immunodeficient NOD-SCID mice." (PMID 39940865, 2025). "Xenografts established from A549 KD TMEM160 cells exhibited significantly lower tumor weights (p = 0.0058) and smaller tumor sizes than those established from A549 CTRL plasmid cells." (PMID 39940865, 2025). "The results demonstrated that TMEM160 knockout significantly reduced the tumor volume from day 20 (p = 0.0006) and continued through the end of the experiment on day 40 (p = 0.01) and weight (p = 0.0005) in HeLa cell xenografts in female NOD SCID mice." (PMID 39940865, 2025). "Furthermore, we showed that a decrease in the expression of TMEM160 leads to reduced tumor growth in vivo." (PMID 39940865, 2025). "From a therapeutic perspective, our study demonstrates that targeting TMEM160 in combination with conventional chemotherapy drugs such as 5-fu significantly enhances the sensitivity of GC cells to chemotherapy and inhibits tumor growth both in vitro and in vivo." (PMID 40223081, 2025). "Also, we discovered that the knockdown of TMEM160 decreased cell proliferation and migration in vitro and decreased tumor growth in vivo." (PMID 39940865, 2025). "Given that the KEAP1/NRF2 antioxidant signaling pathway regulates ROS and iron metabolism-related genes and is a key negative regulator of ferroptosis in tumor cells, we hypothesized that TMEM160 regulates ferroptosis in GC cells via the KEAP1/NRF2 pathway." (PMID 40223081, 2025). "As the TMEM160 protein was initially identified as being overexpressed in HeLa cells, we evaluated whether TMEM160 knockout in HeLa cells would affect tumor growth." (PMID 39940865, 2025). "Furthermore, the downregulation of TMEM160 significantly restricted tumor growth in immune-competent BALB/c mice." (PMID 38454413, 2024). "WB and IHC analysis of subcutaneous tumor tissues in the CDX and PDX models showed that TMEM160 knockdown reduced the expression of NRF2 and its target genes, GPX4 and SLC7A11." (PMID 40223081, 2025). "Our results showed that TMEM160 protein exhibited a median expression HR score of 120 (range 50–247.5), with predominant localization in the cytoplasm of the cells, while in the adjacent non-tumor tissue, the signal for TMEM160 was negative." (PMID 39940865, 2025). "In addition, we observed nuclear and cytoplasmic localization of TMEM160 in both tumor and non-tumor cells of the lung and cervix." (PMID 39940865, 2025). "TMEM160 inhibits the degradation of PD‐L1 that, in turn, fosters the malignant progress, radio‐resistance and immune evasion of CRC cells, while VKR‐2 is a kinase effector of signaling pathways that regulate apoptosis and tumor cell growth, also through PD‐L1 network." (PMID 39992019, 2025). "Regarding functionality, the absence of TMEM160 significantly inhibited the proliferation, invasion, metastasis, clonogenicity, and radioresistance of CRC cells, while simultaneously enhancing the cytotoxic effect of CD8 + T cells on tumor cells." (PMID 38454413, 2024).
TMEM160 also shares sentences with these, for which no sentence is quoted: adenocarcinoma (1 paper); cervical adenocarcinoma (1); COVID-19 (1); gastric cancer (1); non-small cell lung carcinoma (1); squamous cell carcinoma (1).